CAV2 (caveolin 2)
Diseases named in the same sentence as CAV2 in open-access papers (continued):
Sharing a sentence is not in itself a finding about the gene and the disease.
tumor (continued). "The remarkable reduction in LLC and CMT 167 tumor volume in Cav-2 KO mice on day 17 coincided with equally dramatic reduction in tumor size and mass determined upon surgical tumor removal followed by photographing and weighing." (PMID 31831780, 2019). "In this study, we showed that the expression of CAV1 and CAV2 is deregulated in stromal cells of the primary tumor as well as in the stroma of lymph nodes." (PMID 29850392, 2018). "The role of Cav-1 and Cav-2 in endothelial proliferation and differentiation during fibrosis requires further investigation, because both apparently interfere with tumor-induced angiogenesis in distinct ways." (PMID 29250058, 2017). "CAV1 and CAV2 were correlated with tumour growth and metastasis, and FN1 was a potential biomarker for some cancers, while ITGA1 and THBS1 were also associated with cancer risk." (PMID 27557147, 2016). "More importantly, syndecan-2 expression was upregulated in lymph node samples compared directly with the primary tumours and in triple negative cases, expression of syndecan-2 and caveolin-2 were correlated." (PMID 25623282, 2015). "In a recent study, Shatseva and colleagues have shown that miR-199a-3p modulates tumour cell proliferation as well as survival by regulating CAV2." (PMID 23826261, 2013). "Nevertheless, there is evidence in tumor cells that Cav1 and Cav2 are up-regulated by PPARγ in human carcinoma cells; annexin II is up-regulated by PPARγ agonists in 3T3-L1 cells and Cav1 is suppressed by Ras-p42 MAP kinase and PKA." (PMID 20574519, 2010). "Within the group there are regions coding for genes TES, CAV1 and CAV2, which perform tumor suppressor activities." (PMID 19919683, 2009). "Additionally, opposing effects of Cav-1 and Cav-2 have been noted in tumor-induced angiogenesis, suggesting that Cav-2 is not only a partner of Cav-1 in caveolae formation but also assists in fine-tuning basic cellular processes in a counterbalancing manner." (PMID 40041164, 2025). "Moreover, upon co-culture with tumor cells, we observed that Cav2 redistributed along the axons in a subset of neurons, while in most neurons Cav2 remained primarily localized to the Golgi apparatus." (PMID 41330921, 2025). "Our hypothesis suggests that Cav2+ nerves may facilitate a metabolic transition toward oxidative phosphorylation in tumor cells, thus conferring stemness characteristics." (PMID 41330921, 2025). "In addition to carrying the Braf gene, chromosome 6 carries several genes that are highly expressed in the LNM and tumor populations (Aqp1, Col1a2, Cav1, Cav2, Ptn, RaRes2, Fkbp9, Actg2, Ybx3, Mgp, Sox5, Kcna1, and Ptms)." (PMID 40571713, 2025). "Furthermore, we compared lactate secretion from tumor cells co-cultured with Cav2+/+ and Cav2-/- TG." (PMID 41330921, 2025). "Grzegorz Sowa Host’s team observed that CAV2-knockout mice displayed reduced tumor growth and microvascular density, indicating that CAV2 may promote tumor growth by supporting tumor-induced angiogenesis." (PMID 36114176, 2022). "Moreover, knockout of CAV2 suppressed tumor metastasis, and RNA-seq and bioinformatics analyses indicated that CAV2-related mRNAs were mainly enriched in pathways involved in metastasis." (PMID 36114176, 2022). "CAV2 was demonstrated to be a key regulator of S100 protein expression that upregulates the proteins levels of S100s, which promotes the invasion and migration and downregulates the expression of tumor suppressors." (PMID 36114176, 2022). "Given that overexpression of both BRD4 and CAV-2 are observed in PC, targeting the BRD4-CAV-2 interaction by developed BET inhibitors may be applicable to prevent tumor growth in PC." (PMID 32099528, 2020). "Similar to Cav-1, Cav-2 involvement in tumorigenesis seems to depend on the tumor type." (PMID 33195223, 2020). "To investigate if the immune cell types may be involved in tumor rejection observed in Cav-2 KO immunocompetent mice, we used a multi-color flow cytometry approach." (PMID 31831780, 2019).
tumor (continued). "Taken together, these data suggest that the increased T cell and macrophage infiltration into LLC tumors may contribute to the anti-tumor phenotype observed in Cav-2 KO mice implanted with LLC cells." (PMID 31831780, 2019). "To determine if WT bone marrow could potentially enable tumor growth in Cav-2 KO mice, we also performed reverse experiments, in which bone marrow from WT mice was transferred into Cav-2 KO mice." (PMID 31831780, 2019). "There may be other reasons for these findings because two other groups injected tumor cells subcutaneously in Cav-1- and Cav-2−/− mice getting results similar to those from the Capozza study." (PMID 29250058, 2017). "Caveolin-1 and Cav-2 show opposite effects in distinct studies of tumor-induced angiogenesis." (PMID 29250058, 2017). "The syndecan-2/caveolin-2 relationship may provide an important insight into regulation of a specific membrane microdomain in tumour, and perhaps untransformed cells." (PMID 25623282, 2015). "Recently, it was shown that CAV2 has pleiotropic effects on proliferation of tumour cells." (PMID 23826261, 2013). "Consequently, we continue to explore the impact of glial cell-derived Cav2 on tumor growth." (PMID 41330921, 2025). "Additionally, to evaluate the role of endothelial Cav2, we co-cultured tumor cells with HUVECs (human umbilical vein endothelial cells) infected with either shCAV2 lentivirus or control lentivirus, and measured the mitochondrial superoxide level in tumor cells." (PMID 41330921, 2025). "Thus, neural Cav2 appears to regulate OXPHOS by orchestrating the secretion of a wide array of metabolism-related proteins rather than simply affecting a single cytokine or signaling pathway in tumor cells." (PMID 41330921, 2025). "Additionally, CAV2 has been mapped to a known tumor suppressor locus within a fragile site that is frequently deleted in human cancers and thus may have a tumor suppressor role." (PMID 37686244, 2023). "Thus, we hypothesized that Cav-2 KO bone marrow-derived hematopoietic cell types should be able to suppress LLC tumor growth in WT mice." (PMID 31831780, 2019). "In addition, the enhanced antigen presentation and T cell activation by M1-like TAMs and dendritic cells could possibly further contribute to increased CD4 and CD8 T cell infiltration, activation and ultimate tumor eradication observed in Cav-2 KO mice." (PMID 31831780, 2019). "The average tumor mass was approximately 1.78 ± 0.52 g and 0.56 ± 0.20 g for WT mice without bone marrow transfer and for WT mice with Cav-2 KO bone marrow transfer, respectively, resulting in significant (p < 0.05) and nearly 3-fold reduction in tumor mass by Cav-2 KO bone marrow transfer." (PMID 31831780, 2019). "While CAV2 and TMED2 exhibited widespread expression in both tumor cells and stromal cells, PLAU demonstrated a relatively specific expression pattern in CAFs and myeloid cells." (PMID 39834857, 2025). "Building upon our prior demonstration that Cav2 predominantly localizes within the nerves of the HNSCC microenvironment, we sought to elucidate the effects of neural-specific Cav2 ablation on tumor progression." (PMID 41330921, 2025). "Combined with the immunohistochemical data from the database, we investigated the protein level changes of CAV2, FLT1, THBS3 and VAV3 in tumor samples and normal control samples." (PMID 36950136, 2023). "Treatment with IL30 also upregulated tumor progression genes, such as Ar (3.27 times), Bcl2 (3.25 times), IL6 (3.90 times), Cav2 (7.60 times), Ndrg3 (4.5 times), Sept7 (4.10 times) and Sfrp1 (7.46 times)." (PMID 36224639, 2022). "Remarkably, we have also found that the expression of PD-L1, which has an immunosupressive function in the anti-tumor immune reaction, correlated inversely with EMT transcription factors related to barriers (CDH2, CAV2, DSC2, and IL1RN)." (PMID 34527572, 2021).
tumor (continued). "Cav-1 and Cav-2 were reported to be regulated by FGFR4 and CDH2 and, also, correlated with tumor progression, invasion and metastasis." (PMID 33809909, 2021). "Univariate survival analysis revealed that, in addition to clinical stage, tumor differentiation, nervous invasion and vessel invasion, high BRD4 (HR = 3.321, p = 0.001) and CAV-2 expression (HR = 3.666, p < 0.001) predicted poor prognosis." (PMID 32099528, 2020). "Given well established role of cytotoxic CD8 T cells in the anti-tumor response, often leading to tumor regression, it was within our expectation that LLC tumors from Cav-2 KO mice were infiltrated with more CD8 T cells." (PMID 31831780, 2019). "The number of MHC IIhi (M1-like) TAMs was increased in LLC tumors co-injected with Cav-2 KO bone marrow cells relative to both CD11b+F4/80+ TAM populations and to total cells in tumor." (PMID 31831780, 2019). "Interestingly, although the ratios of M1-like to M2-like TAMs are still considerably high in the tumor microenvironment of WT mice, tumors continue growing, which may be due to insufficient numbers of infiltrating M1-polarized TAMs in WT compared to Cav-2 KO mice." (PMID 31831780, 2019). "BIRC3, CAV1, CAV2, FN1, ITGA1 and THBS1 were functionally enriched to focal adhesion, which contributes to antiangiogenic and anti-tumour effects." (PMID 27557147, 2016). "Cav-1 and Cav-2 genes are located in a fragile site (known as D7S522 locus) that is frequently deleted in human cancers, indicating a common role as tumor suppressors." (PMID 24427291, 2014). "Although CDC42 was predicted to be a miR-199a-3p target, CAV2 and CDC42 possessed negatively correlated expression in the studied tumour cell line MT1." (PMID 23826261, 2013). "Given that Cav2 is expressed in neurons, glial cells, and vascular endothelial cells, we sought to explore the impact of Cav2 expression in specific cell types on the OXPHOS phenotype of tumor cells." (PMID 41330921, 2025). "It was found that mitochondrial superoxide level in tumor cells co-cultured with Cav2+/- non-neuronal cells was also reduced compared to the control group." (PMID 41330921, 2025). "While TCGA datasets derive from bulk tumor sequencing, the specific cellular source of CAV2 in the tumor microenvironment has not been well delineated." (PMID 41330921, 2025). "Examining its clinical relevance, we found no significant ties between CAV2 expression and clinical tumor (T) or nodal N stages." (PMID 41330921, 2025). "Moreover, we also checked the protein–protein interaction (PPI) network of CAV1 and found it is highly connected with Caveolin-2 and EGFR, which are important factors for tumor progression." (PMID 37642765, 2023). "Furthermore, the in vivo and in vitro experiments with PDX models also demonstrated miR-144 played anti-tumor roles through targeting FGF7 and CAV2." (PMID 32139705, 2020). "Since the early tumor-infiltrating macrophages are typically M1-polarized, we hypothesized that the earliest palpable LLC tumors from Cav-2 KO mice would have increased levels of M1-polarized macrophage-produced cytokines." (PMID 31831780, 2019). "Although in addition to TAM, bone marrow is the origin of several other immune cell types, we already demonstrated that Cav-2 deficient TAMs rather than CD4 and CD8 T cells initiate anti-tumor cascade." (PMID 31831780, 2019). "In addition, further studies will be necessary to prove the direct relationship between Cav-2 and TAM in regulating tumor growth and anti-tumor immune response." (PMID 31831780, 2019). "Taken together, our data from bone marrow transfer experiments suggest that bone marrow-derived hematopoietic cell types from Cav-2 KO mice inhibit LLC tumor growth in WT mice, and that bone marrow-derived TAMs are possibly involved in this anti-LLC tumor phenotype." (PMID 31831780, 2019). "More importantly, syndecan-2 and caveolin-2 staining were significantly elevated in cancer patient samples compared to normal tissues regardless of tumor grade." (PMID 25623282, 2015).
tumor (continued). "Although we detected some inter-individual variability, we noticed that the expression level of CAV2 gene was quite constant among samples in the NT condition and only in few cases were CAV2 mRNA levels higher than in non-paired tumor samples (data not shown)." (PMID 24194935, 2013). "Despite the widespread expression of Cav2 in non-neuronal cells of the TG (primarily satellite cells and Schwann cells, along with a small number of fibroblasts), its expression levels were not significantly altered by interaction with tumor cells." (PMID 41330921, 2025). "On the other hand, involvement of Cav-2 in tumor biology was not investigated until recently." (PMID 33195223, 2020). "Furthermore, the in vivo experiments in PDX models displayed the anti-tumor function of miR-144, which could be retrieved by overexpression of FGF7 and CAV2." (PMID 32139705, 2020). "Thus, the impairment of tumor-induced angiogenesis in Cav-1−/− mice was attributed to the absence of Cav-1 and not of Cav-2." (PMID 29250058, 2017). "In this work, we demonstrate that nerves expressing Cav2, compared to those lacking Cav2, drive HNSCC cells to adopt a mitochondrial oxidative phosphorylation phenotype to maintain tumor stemness." (PMID 41330921, 2025). "Thus, the high M1-like TAM/M2-like TAM ratios in early stage tumors (observed in both WT and Cav-2 KO mice) may not be sufficient to suppress tumor growth without the overall increase in numbers of infiltrating M1-like TAMs (as observed in tumors from Cav-2 KO mice)." (PMID 31831780, 2019). "We found that CAV2 and VAV3 were significantly highly expressed in tumor samples, whereas the expression levels of THBS3 and FLT1 were not significantly altered in tumor samples." (PMID 36950136, 2023). "Additionally, CAV2 expression lacked correlation with lymphovascular invasion and extracapsular extension (ECE), suggesting its selective influence on neural rather than global tumor invasiveness." (PMID 41330921, 2025).
cancer (52 papers, 2004 to 2025). A tumor composed of atypical neoplastic, often pleomorphic cells that invade other tissues. "CAV-2 plays a key role in intracellular cell transport and higher level of CAV-2 is associated with different types of cancer progression." (PMID 34078402, 2021). "Among these genes, our previous studies demonstrated that ITGA3, ITGA6, and CAV2 were overexpressed in cancer tissues and associated with cancer cell migration and invasion." (PMID 28415821, 2017). "Moreover, Cav2-expressing nerves are implicated in shifting cancer cell metabolism towards mitochondrial oxidative phosphorylation, a process involved in maintenance of cancer stem cells (CSCs)." (PMID 41330921, 2025). "Higher level of CAV-2 has been associated with different types of cancer progression." (PMID 32099528, 2020). "Additional mRNAs, involved in EMT and target of FMRP in cancer cells, such as Microtubule Associated Protein 1B (Mtap1b), Caveolin 2 (Cav2), Desmoplakin (Dsp), Keratin 14 (Krt14), Microphthalmia-Associated Transcription Factor (Mitf) were similarly regulated at the level of translation." (PMID 24092663, 2013). "The results indicated that only 1/10 of these mice developed invasive cancer, highlighting the significance of glial cell-derived Cav2 in the initiation of HNSCC." (PMID 41330921, 2025). "Our results also demonstrate that Cav2-expressing nerves confer stemness properties to cancer cells." (PMID 41330921, 2025). "As mentioned in HCC and CC, CAV2 targeting results in differential results depending on the cancer type." (PMID 40862737, 2025). "Investigating the influence of cancer cells on neural Cav2 expression, trigeminal ganglia (TGs) were co-cultured with SCC15 and MOC2 cells in vitro for a 5-day period." (PMID 41330921, 2025). "Collectively, our results indicate that Cav2+ nerves drive a transition to an enhanced mitochondrial respiratory character in cancer cells." (PMID 41330921, 2025). "Here, we elucidate the critical involvement of neural Cav2 in the interaction between nerves and cancer cells in HNSCC." (PMID 41330921, 2025). "Here the authors show that HNSCC cancer cells promote the expression of caveolin-2 (Cav2) on neural cells, while Cav2-expressing neurons or glial cells induce a mitochondrial oxidative phosphorylation phenotype in cancer cells to maintain cancer stemness." (PMID 41330921, 2025). "Co-expressed genes (PXN, ITGA3, TES, and MET) were identified and analyzed by FunRich with CAV1 and CAV2, revealing a significant correlation with focal adhesion (p < 0.001), which has a vital influence on cancer progression." (PMID 36830672, 2023). "Cav-2 also has dual functions of inhibiting and promoting cancer and can be expressed in combination with Cav-1 or play a regulatory role alone." (PMID 37828916, 2023). "The results exhibited that the mRNA and protein expression levels of PLAU, APP, AREG and CAV2 were upregulated in cancer cells compared to normal cells." (PMID 36437265, 2022). "As members of the CaV1 subfamily, different CaV2 channels have been reported to be dysregulated in cancer." (PMID 32575381, 2020). "In another study, investigating whether Caveolin-2 (CAV2) expression modulation could have a therapeutic interest, it was found that CAV2 expression has differential outcomes in each cancer type." (PMID 40862737, 2025). "Based on this, a link between Cav2-expressing nerves and cancer cell stemness was established." (PMID 41330921, 2025). "Few studies on the function of caveolin-2 in cancer are available, and the role of CAV2 in HNSCC remains unclear." (PMID 36114176, 2022). "CAV2 mRNA was also found to be lower expressed in cancer tissues in 32 datasets." (PMID 34513683, 2021). "In addition, extracellular matrix (ECM)–receptor interaction and focal adhesion pathways were commonly caught in both cancer types, but all the corresponding bicluster targets except two (CAV2, BIRC2) were also included in PI3K/Akt signaling pathway." (PMID 30820547, 2019).